IKZF1 (IKAROS family zinc finger 1)
Diseases named in the same sentence as IKZF1 in open-access papers (continued):
Sharing a sentence is not in itself a finding about the gene and the disease.
cancer (continued). "Our DNA-methylation-based predictors selected CpG sites and CGIs related to genes previously found individually involved in cancer development and with transcriptional activity regulated by methylation (e.g. MBTPS2, YY2, ECRG4, IKZF1)." (PMID 31708973, 2019). "Detectable methylation in one or both genes was present in 98.9% (90/91) of cancer tissue, with methylated BCAT1 present in 89/91 (97.8%) and methylated IKZF1 present in 79/91 (86.8%)." (PMID 29796114, 2018). "Sensitivity of the methylated BCAT1/IKZF1 blood test for recurrence was 75.0% in patients with stage II cancer at diagnosis (6/8), 70.6% of the stage III cancers (12/17), and 33.3% of the stage IV cancers (1/3)." (PMID 27726312, 2016). "Of the genes tested in plasma, BCAT1, GRASP, IKZF1, IRF4, SDC2, SEPT9 and SOX21 exhibited high sensitivity (≈55% or greater) for detection of methylated ctDNA in cancer patients." (PMID 27983717, 2016). "A total of 41/74 cancer cases were positive for both methylated BCAT1 and IKZF1 DNA compared to only 1/144 control)." (PMID 25928810, 2015). "Of the 129 cancer cases, 57 % were methylation positive for BCAT1 and 48 % for IKZF1, with 66 % methylation positive by either gene." (PMID 26445409, 2015). "A two-gene classifier model (“either or” rule) improved segregation of CRC from controls, with 57 of 74 cancers (77%) compared to only 11 of 144 (7.6%) controls being positive for BCAT1 and/or IKZF1 DNA methylation." (PMID 25928810, 2015). "By fitting models of cancer classification (controls, early or late cancer), we show the potential of using the level of methylated BCAT1 and/or IKZF1 DNA in blood to estimate the probability of a positive result being due to the presence of cancer." (PMID 25928810, 2015). "The relationship between measured levels of circulating methylated BCAT1 or IKZF1 DNA in plasma and cancer stage was modeled to estimate the likelihood of cancer, given a methylated BCAT1 or IKZF1 DNA mass estimate per triplicate assay." (PMID 25928810, 2015). "We identified genes for which ASEs were observed in both the Afro-Caribbean cohort and the Jurkat cells expressing Tax or HBZ, including cancer genes EIF4A2, IKBKB, LZTR1, STAT6 (for Tax); CARS, MDM2, IKZF1 (for HBZ); and EWSR1, MUTYH, and PTPRC (for both Tax and HBZ)." (PMID 34543356, 2021). "A prospective correlative biomarker study between presence of methylated BCAT1 and IKZF1 in tissue and blood was conducted in cases with CRC to explore how detection of such ctDNA biomarkers relates to cancer characteristics, methylation in tissue and surgical resection of the primary cancer." (PMID 29796114, 2018). "Significant methylation of either BCAT1 or IKZF1 was seen in 86/91 (94.5%) cancer tissues, with levels independent of stage and higher than that observed in adjacent non-neoplastic specimens (P < 0.001)." (PMID 29796114, 2018). "Unfortunately, we could not assess whether detectability of methylated BCAT1 and IKZF1 DNA in blood was associated with appearance of vasculature-related features, as these variables were not recorded in the histological reports for the cancers included in the dataset herein." (PMID 25928810, 2015). "Our own dataset only included four Stage I cancers, and while two (50%) of these were detected, the sample numbers are presently too low to conclude whether the methylated BCAT1/IKZF1 test will give good detection of Stage I cancers." (PMID 25928810, 2015). "Screening of our library of CRBN-directed molecular glues against a panel of pediatric cancer cell lines led to the identification of SJ7095 with high cytotoxicity against MOLM-13 cells (IC50 = 71 nM), and potent CRBN-dependent degradation of CK1α, IKZF1 and IKZF3 proteins." (PMID 38228616, 2024). "Moreover, from a wide range of human cancers we know that there is extensive cross-talk between AKT and MAPK/ERK signaling, we observed that inhibition of AKT alone resulted in partial suppression of ERK phosphorylation in both control and IKZF1-/- cells." (PMID 36119546, 2022).
cancer (continued). "Although the roles of another four genes (SCUBE2, PRKCB, IKZF1, and MAP4K1) in NPC were not known, their functions were reported in other cancer types." (PMID 33403044, 2021). "Our analysis also revealed ectopic rearrangements affecting multiple known cancer genes, some of which bore the hallmarks of RAG activity (e.g., Ikzf1, Kremen1), while others lacked RSS-like motifs at breakpoint junctions (e.g., Notch1, Pten)." (PMID 31167132, 2019). "The presence of methylated BCAT1 and IKZF1 DNA in blood is not likely to be limited to CRC only 24, 35, and as reported here, three of six cases diagnosed with other cancers were positive with the BCAT1/IKZF1 test." (PMID 27726312, 2016). "We modelled the relationship between disease severity (non-cancer, early stage cancer and late stage cancer) and the fraction of methylated BCAT1 and IKZF1 DNA." (PMID 26445409, 2015). "From limited sample material, we detected integration events in 2,749 cells and found no integration events at genomic loci associated with clonal expansion after gene therapy near LMO2, IKZF1, CCND2, HMGA2, or MECOM, and no overrepresentation near cancer-related genes." (PMID 39532107, 2025). "HCCs exhibited underexpression of IKZF1 mRNA levels compared with their corresponding non-tumorous livers; however, MDIG mRNA was expressed at high levels in HCC samples compared with the matched non-cancer liver tissue, and a similar result was obtained in a TCGA cohort." (PMID 28471446, 2017).
hematologic malignancies (11 papers, 2014 to 2025). "The overexpression of IKZF1/3 is closely associated with the development of several hematologic malignancies." (PMID 39169396, 2024). "This further illustrates hematological malignancies on the basis of germline IKZF1 variants, and sometimes additional somatic variants identified in hematological progenitors." (PMID 38813543, 2024). "In addition, in OS, we unexpectedly identified that IKZF1, a factor primarily associated with hematologic malignancies, is linked to the upregulation of PD-L1 expression in OS cells." (PMID 39983717, 2025). "Exhibiting superior efficacy over parallel drugs designed for the same purpose in hematologic malignancies, such as CC-220 and lenalidomide, CC-99282 delivers accelerated, more profound, and longer-lasting IKZF1/3 degradation." (PMID 39169396, 2024). "Dysfunction of IKAROS also bears paramount significance in leukemic transformation and alterations of IKZF1 gene predicts a poor prognosis in hematological malignancies." (PMID 38978740, 2024). "Associations with hematologic malignancies are not restricted to somatic variants and have been reported in 2009 for germline IKZF1 variants and ALL." (PMID 38813543, 2024). "Among the downregulated master regulators, MYB and BCL11A have been related to immune system regulation in hematologic malignancies, suggesting their participation in the maintenance of the hematopoiesis and in the regulation of other downregulated master regulators such as IKZF1." (PMID 32260546, 2020). "Degradation of IKZF1 and IKZF3 is therapeutically exploited in the treatment of hematological malignancies." (PMID 32811853, 2020). "By binding cereblon (CRBN), thalidomide can activate the E3 ubiquitin ligase CRL4CRBN-mediated ubiquitination and degradation of the IKAROS family transcription factors IKZF1 and IKZF3, which play key roles in the tumorigenesis and progression of hematologic malignancies." (PMID 34530760, 2021).
infection (5 papers, 2022 to 2025). The state of being infected such as from the introduction of a foreign agent such as serum, vaccine, antigenic substance or organism. "Our investigation revealed a notable upregulation of the transcription factor IKZF1 across various infection-associated inflammatory conditions." (PMID 41019036, 2025). "This conserved expression pattern across diverse infection models suggested a fundamental role for IKZF1 in macrophage-mediated inflammatory responses." (PMID 41019036, 2025). "To fine-tune IKAROS levels without the toxicities associated with shRNA infection and lenalidomide treatment, we generated IKAROS-regulatable models by overexpressing a codon-optimized version of IKAROS fused to a degron tag32 and knocked out the endogenous IKZF1 gene." (PMID 40268897, 2025). "Next, we generated reconstituted cell lines stably expressing AGIA-AirID-CRBN-WT (wild type) or -YW/AA by infection of CRBN−/− HEK293T cells with lentivirus, and we performed STA-PDA using the reconstituted HEK293T cells transiently transfected with Myc-SALL4 and Myc-IKZF1 expression vectors." (PMID 35013300, 2022).
blood cancers (2 papers, 2023 to 2026). "PROTACs that target Bruton's tyrosine kinase have shown great response rates in B-cell cancers, and molecular glues that target Ikaros family proteins (IKZF1/3) are still helping people with blood cancers." (PMID 42254124, 2026). "Furthermore, preclinical evidence suggests a therapeutic implication of immunomodulatory imide drugs (IMiDs) and targeted therapy in the context of altered IKZF1 in a variety of hematological neoplasms." (PMID 37833543, 2023).
gonadal disease (1 paper, 2024). "Despite the limited sample size, it is interesting to note that every patient with hyperleukocytosis (n=2), CNS-3 disease (n=2), gonadal disease (n=1), and IKZF1 alterations (n=5) developed R/R disease." (PMID 38496108, 2024).
IKZF1 also shares sentences with these, for which no sentence is quoted: myeloproliferative neoplasm (5 papers); rheumatoid arthritis (4); diabetes (3); hematologic cancers (3); hepatocellular carcinoma (3); liver cancer (3); anemia (2); atopic dermatitis (2); B cell lymphoma (2); bacterial infections (2); Kabuki syndrome (2); myeloid leukemia (2); Thrombocytosis (2); thrombosis (2); acute promyelocytic leukemia (1); adenocarcinoma (1); allergic disease (1); autoimmune hepatitis (1); autoimmune lymphoproliferative syndrome (1); autoimmune uveitis (1); bone marrow failure (1); breast tumors (1); cardiomyopathy (1); cavernous cerebral malformation (1); cervical adenocarcinoma (1); chronic lymphocytic leukemia (1); chronic obstructive pulmonary disease (1); colorectal tumors (1); combined immunodeficiency syndrome (1); congenital disorder of glycosylation (1).
A further 38 diseases each share a sentence with IKZF1 in 1 paper.